VIM (vimentin)
Diseases named in the same sentence as VIM in open-access papers (continued):
Sharing a sentence is not in itself a finding about the gene and the disease.
lung carcinoma (continued). "Indeed, DEK overexpression in vitro was associated with an increase in EGFR, KRAS, and vimentin levels in lung cancer cell lines and poor prognosis according to patient database analyses." (PMID 39852534, 2025). "In addition, the E‐cadherin and vimentin expression are associated with metastasis of lung cancer patients." (PMID 39466654, 2024). "Indeed, the role of EMT in the tumorigenesis of different cancers, including lung, and the association of E-cadherin loss and vimentin expression with the malignant phenotype of non–small cell lung cancer (NSCLC) is well known." (PMID 39337653, 2024). "Importantly, PAK1 acts as a potential EMT inducer by stimulating Vimentin expression, thereby inducing E-cadherin loss in lung cancer cells." (PMID 37225681, 2023). "Furthermore, EMT is essential for tumor progression toward a metastatic state and Vimentin expression was associated with tumor progression and invasion in breast and lung cancer." (PMID 33526844, 2022). "Moreover, pre-treatment vimentin expression in clinical specimens obtained from patients with ALK-rearranged lung cancer was associated with poor ALK-TKI treatment outcomes." (PMID 35042943, 2022). "In lung cancer, PD-L1 score was positively associated with Snail and vimentin expression." (PMID 33810560, 2021). "In addition, the expression of PTEN, MYC, EGFR, and Vimentin, potential indicators associated with lung cancer patients survival period, was also detected in A549 lung cancer cells." (PMID 31508368, 2019). "Interestingly, loss of BRG1 induced metastasis in human lung cancer cells by driving E-cadherin loss and VIM upregulation." (PMID 31652979, 2019). "The association we found between EMT molecular signatures and ALK rearrangements in NSCLC is consistent with the frequent observation of the loss of E-cadherin associated with vimentin expression in ALK-rearranged lung cancer compared with other NSCLC genotypes." (PMID 27119231, 2016). "Additionally, vimentin is a gold-standard marker of epithelial–to-mesenchymal differentiation during malignancies, and is also proposed as a diagnostic and prognostic marker in lung cancers." (PMID 35573702, 2022). "The twenty human lung cancer cell lines were screened through pattern of E-cadherin and vimentin using Western blot analysis on the basis of definition of epithelial mesenchymal transition, which is a fibroblastoid phenotype, loss of E-cadherin, and gain of vimentin." (PMID 25462870, 2014). "Our findings align with recent studies highlighting the importance of CTCs in predicting treatment outcomes, but extend this knowledge by focusing on specific biomarker phenotypes (CK−/PD-L1+/VIM+) and their clinical relevance in advanced lung cancer." (PMID 41541685, 2026). "Vimentin is known to be overexpressed in various epithelial malignancies, including breast, gastrointestinal, prostate, central nervous system, lung cancers, and malignant melanoma." (PMID 40061451, 2025). "studies demonstrate APOE-mediated angiogenesis via VEGF upregulation in bladder cancer, while lung cancer research reveals its EMT-inducing capacity through ZEB1/vimentin axis activation." (PMID 41390817, 2025). "Characterization of the tumor suppressive role of LncPTEN1 in cancer progression via modulating Trim16 mediated Vimentin degradation provided promising therapeutic target for lung cancer metastasis." (PMID 40521243, 2025). "In a preclinical study employing a Cre-dependent LSL-KrasG12D/Lkb1fl/fl lung cancer model, vimentin was expressed in CAFs surrounding collective invasion packs of epithelial tumour cells, and whole-body vimentin knockout led to a reduction of invasion packs." (PMID 39780187, 2025). "Specifically, MP28 markedly reduced vimentin expression and the migration and invasion ability of lung cancer cells." (PMID 41440915, 2025).
lung carcinoma (continued). "The collective evidence from our investigation demonstrates that LncPTEN1 represents a novel tumor-suppressive lncRNA which inhibits lung cancer metastasis through promoting the degradation of Vimentin and inhibiting the EMT progress." (PMID 40521243, 2025). "Compared with those in PC9 lung cancer cells, the protein expression of Vimentin and N-cadherin, which are related to migration and invasion, were increased." (PMID 39754146, 2025). "α5-nAChR via STAT3/Jab1 signaling cascade facilitates EMT and metastasis in lung cancer cells, accompanied by enhanced N-cadherin and vimentin expression." (PMID 40143965, 2025). "We found that CAFs significantly induced NFs to acquire CAFs properties (called CEFs), including upregulation of α-SMA and Vimentin, enhanced proliferation and migration, and increased ability to promote lung cancer cell migration." (PMID 40199862, 2025). "Western blotting assay showed that 20 μM and 40 μM ROB acted on lung cancer cells and increased the expression of E-cadherin and decreased the expression of N-cadherin and Vimentin protein compared with the control group." (PMID 39450260, 2024). "Our analysis of the TCGA data revealed significantly lower E‐cadherin mRNA levels in high‐stage lung cancer tissues, along with significantly higher vimentin mRNA levels." (PMID 39466654, 2024). "PARP-1 was also shown to transcriptionally regulate vimentin by binding to the promoter of vimentin in lung cancer cells." (PMID 39201718, 2024). "Our Cancer Genome Atlas results revealed that E‐cadherin levels were markedly lower in lung cancer patients than in healthy controls, while vimentin levels were markedly higher." (PMID 39466654, 2024). "We also present ALD-R491 as a potential novel drug against EMT and lung cancer metastasis, and describe the changes of the vimentin interactome that accompany TGF-β1-induced EMT, with the most significant change in components of the extracellular matrix." (PMID 39796712, 2024). "Vimentin expression is also required for the development and metastasis of lung cancer cells in mice." (PMID 39796712, 2024). "The expression of vimentin was higher, accompanied by significant degradation of E‐cadherin, resulting in diminished cell–cell adhesion in high metastatic lung cancer tissues." (PMID 37850256, 2024). "We used a 3D-matrix based microfluidic platform to demonstrate the potentiating effect of IF on exogenous TGF-β induced upregulation of the Smad-signaling activity and the expression of mesenchymal marker vimentin in A549 lung cancer spheroids." (PMID 38087979, 2024). "IL-6 facilitates epithelial to mesenchymal transition in lung cancer increasing vimentin expression, and in colorectal cancer via integrin β6 upregulation." (PMID 36982207, 2023). "exATP hastened EMT, mobility, and invasion, increased MMP expression, increased levels of EMT-transcription factors (vimentin, Snail, and Slug), and decreased epithelial markers in lung cancer cells." (PMID 36741002, 2023). "In vivo treatment of TiY exhibits a therapeutic effect on lung cancer tumors via targeting TIC expressing soluble vimentin." (PMID 36923526, 2023). "The epithelial OPN regulates lung cancer cell movement, proliferation, and EMT process by activating OPN‐PI3K and OPN‐MEK pathways and re‐organizing the conformational structure of vimentin‐associated cytoskeletons." (PMID 37605313, 2023). "CAFs also deliver the transcription factor Snail homolog 1 (SNAI1) to lung cancer cells via exosomes and induce EMT through cadherin-1 encoding epithelial-cadherin and vimentin (VIM) encoding waveform proteins." (PMID 37122754, 2023). "Inhibition of LINC00511 increased epithelial biomarker (E-cadherin) expression and suppressed mesenchymal biomarkers (vimentin, snail, N-cadherin) to inhibit epithelial–mesenchymal transition of lung cancer." (PMID 36874361, 2023).
lung carcinoma (continued). "Increased vimentin levels are correlated with the tumorigenesis, invasion, and metastasis of several types of cancer, including lung cancer." (PMID 37888708, 2023). "Although TSPAN7 is an anti-tumor factor in bladder cancer, it promoted lung cancer progression by inhibits the expression of E-cadherin and vimentin, which raises the level of N-cadherin." (PMID 36512456, 2023). "Vimentin, a type III intermediate filament, is highly expressed in lung cancer and is associated with metastatic tissue and lower survival rates in patients with NSCLC." (PMID 37161053, 2023). "Western blotting results also revealed the ability of LAMC2 to promote vimentin protein expression, which is highly correlated with the occurrence of metastasis and poor prognosis in lung cancer patients." (PMID 37542131, 2023). "Collectively, these data suggest that vimentin can be pharmacologically targeted in vivo to disrupt the ability of lung cancer cells to invade and migrate away from the primary tumor." (PMID 37161053, 2023). "In a genetic engineering mouse model of lung cancer, vimentin+ CAFs have been found to surround the cancer cells sprouting from the primary tumor to improve lung cancer metastasis." (PMID 37143134, 2023). "High ATP concentrations in lung cancer cell lines favored cell detachment, migration, and invasion, with increased MMPs, vimentin, SNAIL and SLUG expression, and filopodia development and cell protrusions." (PMID 36741002, 2023). "Exosomes derived from transplanted lung cancer cells induce the expression of VIM and EMT in human bronchial epithelial cells." (PMID 37122754, 2023). "Collectively, these data provide evidence that vimentin is integral in the progression and metastasis of lung cancer." (PMID 37161053, 2023). "CAFs isolated from lung cancer tissue promote metastasis by secreting IL-6, which activates JAK2 and STAT3 signaling and also induces EMT via increasing vimentin expression in lung cancer cells both in vitro and in vivo." (PMID 36620544, 2022). "Rh3 treatment (20 and 40 μM) downregulated levels of transcripts of N-cadherin, Vimentin, and Snail and upregulated levels of transcripts of E-cadherin in lung cancer cells." (PMID 35745677, 2022). "Our results herein demonstrated that overexpression of HORMAD1 significantly increased the expression of ZEB-1, N-cadherin, and Vimentin and decreased the expression of E-cadherin in lung cancer cells." (PMID 35347116, 2022). "Western blotting results showed that Rh3 significantly upregulated E-cadherin expression and suppressed N-cadherin, Vimentin, and Snail expression dose-dependently, suggesting that Rh3 decreased metastatic ability in lung cancer cells." (PMID 35745677, 2022). "In this study, we tested the cytotoxicity of a rhenium ligand, Tricarbonylperrhenato(bathocuproine)rhenium(I) (PR7), against a GFP labeled vimentin gene knock in by CRISPR modified EMT model A549 lung cancer cell lines." (PMID 35342659, 2022). "The drug treated CRISPR Cas9 modified vimentin-GFP knock in A549 lung cancer cell lines showed several downregulated and upregulated genes that are involved in cancer biogenesis pathways." (PMID 35342659, 2022). "Previously, the vimentin expression was found to be increased in many cancers, such as colorectal and lung cancer." (PMID 36032170, 2022). "An increase in the cell adhesion factor E-cadherin and a decrease in the mesenchymal stem cell markers N-cadherin and Vimentin in lung cancer cells indicated that AC-P19M reversed the EMT process." (PMID 36555235, 2022). "In lung cancer, increased expression of vimentin is used to identify the progression of epithelial cells from a localised lesion to invasive, metastatic tumour cells." (PMID 35932303, 2022).
lung carcinoma (continued). "In this study, we treated the vimentin knock in A549 lung cancer cell lines with PR7 after inducing EMT by TGF beta treatment and determined the cytotoxic effects of the drug by MTT assay technique." (PMID 35342659, 2022). "EMT-related markers such as E-cadherin and vimentin are associated with prognosis, tumor lymph node metastasis, and tumor stem marker CD133 expression in lung cancer patients." (PMID 35790819, 2022). "Although the trends in expression and organization differed from that observed in our senescent lung cancer cells, it indicates the significance of vimentin dynamics to different models of senescence." (PMID 35122388, 2022). "Vimentin is an intermediate filament protein transported by small EVs and released by the cancer cells whose expression increases in the metastatic stage of lung cancer, resulting in a poor prognosis for the patient." (PMID 35163368, 2022). "In another study, cancer stem cell-derived exosomal miR-210-3p bind and inhibit fibroblast growth factor receptor-like 1 (FGFRL-1) to increase vimentin expression in lung cancer cells." (PMID 35573702, 2022). "In contrast, H1975 cell line from lung cancer only induced VIMENTIN expression at 48 h of co-culture." (PMID 35265204, 2022). "Similar work demonstrated that the interaction of Beclin1 with vimentin affects its USP14 mediated de-ubiquitination leading to abrogated degradation which provides an increased ability of cell migration in lung cancer." (PMID 35573702, 2022). "Repression of MTAP‐dependent symmetric dimethylation mediated by PRMT5 increases vimentin protein stability and leads to invasion and metastasis in MTAP‐deficient lung cancer." (PMID 35766227, 2022). "Recent studies have shown the significance of Vimentin in lung cancer, wherein a high expression of Vimentin was found to be related to a high frequency of metastases and therefore a poor prognosis in patients with resected non-small cell lung cancer." (PMID 35260633, 2022). "Vimentin is not only correlated with but required for lung cancer metastasis, which suggests increased aggressiveness of ATGL-KO spheroid derived tumors." (PMID 33992777, 2021). "We found that compared to normal tissues, the tumor tissues collected from lung cancer patients showed a lower level of TAp63α expression, along with downregulated E-cadherin expression and upregulated Vimentin expression." (PMID 33748140, 2021). "In line with the IHC assay data, western blot analysis confirmed the decreased expression levels of TAp63α and E-cadherin and the increased Vimentin expression level in lung cancer tissues compared to the corresponding relative normal tissues." (PMID 33748140, 2021). "Here, we found that knockdown of FOXH1 significantly decreased the expression of mesenchymal markers (Slug, Snail, MMP2, N-cadherin, and Vimentin), while increasing the expression of epithelial marker (E-cadherin) in lung cancer cells." (PMID 34090445, 2021). "The results showed that vimentin expression was positively correlated with M1 and M2 number in lung cancer, however, negatively correlated with the ratio of M1/M2." (PMID 34158591, 2021). "The clinical relationship between PLK1 or vimentin and cumulative OS in lung cancer was analysed using KM PLOTTER." (PMID 33963314, 2021). "In contrast to the epithelial indicators, vimentin has been described to be strongly overexpressed in highly metastatic lung cancer cell lines and in patients with advanced NSCLC disease." (PMID 34204745, 2021). "Our results indeed confirmed that the levels of the key NMD factor UPF1 were downregulated in patients presenting with lung cancers with high levels of VIMENTIN, a key marker of the EMT." (PMID 34680418, 2021). "In direct immunofluorescence studies, we also found a significant reduction of the N-cadherin and vimentin proteins at concentrations of 5–10 μM in norcycloartocarpin-treated lung cancer cells." (PMID 34383763, 2021).
lung carcinoma (continued). "In an in vitro model of lung cancer, the activity of Rac1 (Ras-related C3 botulinum toxin substrate) was regulated by vimentin via VAV2 (a member of the guanine nucleotide exchange factor-VAV subfamily) to influence cellular junctions." (PMID 34638469, 2021). "The newly discovered coronavirus, SARS-CoV-2, can induce EMT-like changes via upregulation of ZEB1 and AXL in lung cancer cells; vimentin is reported to be the prerequisite for the viral entry into the cell by acting as a co-receptor." (PMID 34638469, 2021). "The role of EMT biomarkers FN1 and VIM and the matric metalloproteinases, MMP-9 and MMP-7, in lung cancer in the background of ALK mutation is under study." (PMID 33091333, 2021). "CAFs deliver the transcription factor SNAI1 to lung cancer cells via exosomes, thereby inducing epithelial transformation via CDH1 encoding E-cadherin and VIM encoding Vimentin." (PMID 34193120, 2021). "In both cell lines, the fluorescence intensity of vimentin in most lung cancer cells co-cultured with CAF-CM or CAF was higher than that co-cultured with NF-CM and control group." (PMID 33637678, 2021). "Here, we show that lung CSC‐derived exosomes promote the migration and invasion of lung cancer cells, up‐regulate expression levels of N‐cadherin, vimentin, MMP‐9 and MMP‐1, and down‐regulate E‐cadherin expression." (PMID 32396269, 2020). "The average capture efficiency of EGFR, Vimentin and FA magnetic spheres used alone and in combination to lung cancer cell lines was 78%, 79%, 82% and 91%, respectively." (PMID 32336066, 2020). "For instance, an anti-vimentin chromobody was generated to evaluate cytoskeletal modification and vimentin fiber formation in epithelial-to-mesenchymal transition, induced by TGFβ, in a lung cancer cell model." (PMID 33353213, 2020). "High expression of SPC24 can negatively regulate E-cadherin, and positively regulate N-cadherin and vimentin and participation in epithelial-mesenchymal transition during lung cancer, affecting tumor growth and invasion." (PMID 32226507, 2020). "Consistent with this possibility, we found that siRNA-mediated silencing of GRP115 in the lung cancer cell lines resulted in upregulation of E-cadherin, an epithelial cell marker, and downregulation of the mesenchymal cell markers N-cadherin and Vimentin." (PMID 33330053, 2020). "As expected, we observed that TIM‐4 down‐regulated expression of EMT markers E‐cadherin, and up‐regulated expression of N‐cadherin, vimentin and slug in lung cancer cells." (PMID 32020709, 2020). "Lung cancer patients tissues illustrated positive associations between Gli1 and EMT markers, including N-cadherin and Vimentin, both of which are associated with increased EMT." (PMID 31931858, 2020). "We also verified that lung CSC‐derived exosomes enhanced the migratory and invasive abilities of lung cancer cells; increased N‐cadherin, vimentin, MMP‐9 and MMP‐1 expression; and decreased E‐cadherin expression." (PMID 32396269, 2020). "We found that erianin suppressed the migration of lung cancer cells by downregulating the mesenchymal markers vimentin, N-cadherin, slug, snail, and MMP-9 and upregulating the epithelial marker E-cadherin." (PMID 32382060, 2020). "These proteins can be used as markers of EMT in lung cancer, including epithelial markers cytokeratin and E-cadherin, and mesenchymal markers fibronectin and vimentin." (PMID 30906781, 2019). "Specifically, these lung-cancer EVs have been found to increase the expression of Vimentin and N-cadherin and decrease E-cadherin and ZO-1." (PMID 31141946, 2019). "In“in vitro” experiments we studied the effect of cigarette smoke extract (CSE) on EZH2/H3K27me3/DAB2IP expression, apoptosis, invasiveness, and vimentin expression in 16HBE, primary cells, and lung cancer cell lines (A549) long-term exposed to CSE." (PMID 31666665, 2019). "We found that over-expression of miR-33a in lung cancer cells down-regulates the expression of β-catenin, vimentin and snail." (PMID 30719208, 2019).